PGR (progesterone receptor)
Diseases named in the same sentence as PGR in open-access papers (continued):
Sharing a sentence is not in itself a finding about the gene and the disease.
lymph node metastasis (95 papers, 2000 to 2025). "Their multivariate analysis identified several clinicopathological factors (lymph node metastases, tumor size, Ki67 levels, and progesterone receptor positivity) as significantly associated with EPClin results." (PMID 39858055, 2025). "Progesterone receptor expression levels below 80% have been found to be a factor that increases the risk of lymph node metastasis, along with increasing tumor size and the presence of lymphovascular invasion." (PMID 40283001, 2025). "We also applied multivariate analysis of the Cox proportional hazards model to evaluate associations of RFS with γ1-adaptin intensity, tumor size, lymph-node metastasis, Stage, ER, PgR, HER2, and Ki-67." (PMID 38265632, 2024). "In contrast, hormone receptor status determined by preoperative biopsy, i.e., loss of progesterone receptor (PR) and double loss of estrogen receptor and PR, were associated with lymph node metastasis." (PMID 36139675, 2022). "A meta-analysis has shown that FOXP3+ Tregs have a significant negative effect on overall survival (OS) in BC patients, and are associated with estrogen and progesterone receptor status, as well as with lymph node metastases." (PMID 34884993, 2021). "In the analysis of clinicopathologic features, rs11889031 CT genotype and T allele were associated with progesterone receptor (PR) status and lymph node metastasis, which were further supported by our validation cohort." (PMID 21917182, 2011). "While it is known that decreased progesterone receptor levels worsen prognosis, it may also be a factor that increases the risk of axillary lymph node metastasis." (PMID 40283001, 2025). "Among the tested clinicopathological parameters, “age over 60 years,” “postmenopausal state,” “presence of lymph node metastasis,” “negativity for oestrogen receptor (ER)” and “negativity for progesterone receptor (PgR)” were positively associated with PI(18:0/20:3) accumulation." (PMID 31819188, 2020). "Positivity to Sox2 has been associated with a larger tumor size, presence of lymph node metastasis, a higher histological grade, a higher Ki-67 proliferation index, and negativity to Estrogen Receptor (ER) and Progesterone Receptor (PR)." (PMID 33553286, 2020). "Furthermore, receptor status in EC provides prognostic information, where loss of estrogen/progesterone receptor (ER/PR) predicts lymph node metastases and poor survival." (PMID 31783595, 2019). "In addition, loss of ERα expression in lymphatic metastasis was also positively associated with the clinical stage (P=0.007), the number of lymph node metastases (P=0.011) and the loss of progesterone receptor expression (P=0.045)." (PMID 28266545, 2017). "Using logistic regression analysis, we found that axillary lymph node metastasis was significantly more frequent in patients with tumor size as well as lymphovascular invasion and progesterone receptor expression levels below 80% in multivariate analysis." (PMID 40283001, 2025). "Many factors, such as tumor type, histological grade, lymph node metastasis, estrogen receptor (ER), and progesterone receptor (PR), affect the treatment response and prognosis of BC." (PMID 40547857, 2025). "CSI was associated with cancer antigen 125, myometrial invasion, adnexal invasion, parametrial invasion, lymph node metastasis, and progesterone receptor." (PMID 40008004, 2025).
lymph node metastasis (continued). "A total of 113 patients were positive for lymph node metastasis (pretreatment) (71.1%), 46.5% were ER positive, 34.0% were PgR positive, and 40.3% were over 80% AR positive." (PMID 35663978, 2022). "6q15 deletion was unrelated to the presence of lymph-node metastases and progesterone receptor status." (PMID 34625909, 2022). "A biopsy of an axillary lymph node metastasis showed a triple negative receptor expression status, while a biopsy of a peritoneum metastasis had a weak positive progesterone receptor expression." (PMID 36289467, 2022). "NEAT1 expression in serum EVs was high and related to lymph node metastasis, progesterone receptor, estrogen receptor and Ki-67 in BC patients." (PMID 33820555, 2021). "N-cadherin expression and clinicopathological factors such as lymph node metastasis, and PgR status were included in the multivariate analysis." (PMID 31947504, 2020). "Chemotherapy is basically indicated for patients with positive axillary lymph node metastasis, and hormone therapy should be added if such patients are ER- and/or progesterone receptor- (PR-) positive." (PMID 32774370, 2020). "The clinicopathological-feature model included seven features: reproductive history, lymph node metastasis, estrogen receptor status, progesterone receptor status, CA153, CEA, and endocrine therapy." (PMID 32989175, 2020). "Univariable analysis showed that tumor size, lymph node metastasis, tumor grade, ER status, PgR status, chemotherapy administration, CEA levels, and CA15-3 levels were significant prognostic factors for DFS." (PMID 29433529, 2018). "The small subgroup with positive expression of ER and PgR included females (2/2 =100%), with stage II lung adenocarcinoma at diagnosis (2/2=100%) and subsequently developing lymph-node metastasis (2/2 =100%)." (PMID 27690341, 2016). "In addition, the histological grade, TNM stages, lymph node metastasis, estrogen receptor (ER), progesterone receptor (PR), human epidermal growth factor receptor 2 (HER-2), and Ki-67 were positively associated with PBK/TOPK expression." (PMID 36171591, 2022). "A number of factors such as histological grade, type and size of tumor, lymph node metastasis, estrogen receptor (ER), progesterone receptor (PR) and human epidermal growth factor receptor 2 (HER2/neu), influence the prognosis and response to the treatment of cancer." (PMID 31890196, 2020). "None of the other clinicopathological parameters analyzed, including age, lymph node metastasis, primary tumor location, tumor grade, tumor size, TNM stage, progesterone receptor expression, Her-2 or Ki-67, were significantly associated with MGMT expression (p >0.05)." (PMID 33033516, 2020). "However, we did not identify significant correlation between tumors with a high % of phospho-Sox2T116-positive cells with patient age, mitotic rate, lymph node metastasis, architecture and the progesterone receptor status." (PMID 29401647, 2018).
lymph node metastasis (continued). "HR-MAS spectroscopic values were compared according to histopathologic variables [tumor size, lymph node metastasis, histologic grade, status of estrogens receptor (ER), progesterone receptor (PR), HER2 (a receptor for human epidermal growth factor), and Ki-67, and triple negativity]." (PMID 23272149, 2012). "C-myc amplification exhibited significant but weak associations with tumour grade (RR = 1.61), lymph-node metastasis (RR = 1.24), negative progesterone receptor status (RR = 1.27), and postmenopausal status (RR = 0.82)." (PMID 11104567, 2000). "Considering the influencing factors such as positive CA125, deep myometrial invasion, adnexal or parametrial invasion, lymph node metastasis, and negative progesterone receptor status, potentially enhances preoperative diagnosis." (PMID 40008004, 2025). "There was a higher proportion of small tumour size, no lymph node metastasis, no distant metastasis, low histological grade, low Ki-67, positive ER and PgR and negative HER2 in screen-detected invasive cancers." (PMID 38454634, 2024). "Univariate analyses showed that lymphatic involvement, lymph node metastasis, PgR-negative, and high N-cadherin expression were statistically significant prognostic factors for RFS (p = 0.002, p = 0.002, p = 0.026, and p = 0.040, respectively)." (PMID 31947504, 2020). "Furthermore, DCISM was associated with more aggressive tumor characteristics like higher rates of oestrogen receptor (ER) and progesterone receptor (PR) negativity, HER2 positivity, and lymph node metastasis." (PMID 28165014, 2017). "Overexpression of MMP-11 correlates with patients having poorly differentiated tumors, lymph node metastasis and lacking progesterone receptor." (PMID 24564996, 2014). "Including anticancer agents is considered acceptable when patients have numerous lymph node metastases (irrespective of tumor subtype), if their cancer is ER- and/or PgR-positive and expressing a low level of Ki67." (PMID 25055938, 2014). "We found statistically significant positive associations between higher prediagnostic T3 levels and larger tumours, occurrence of lymph node metastases, and negative ER and PGR status." (PMID 25060772, 2014). "No lymph node metastasis was found and as the tumour was ER positive and PgR negative, patient was treated only with an aromatase inhibitor upfront and remains free of disease 48 months now since operation." (PMID 18442419, 2008). "Univariate analysis revealed that patients with younger age (<60 years) (P < 0.0001), negative progesterone receptor expression (P = 0.0028), higher Ki67 expression levels (P < 0.0001), and absence of lymph node metastasis (P < 0.0001) were more likely to benefit from pyrotinib treatment." (PMID 40265017, 2025). "Notably, the stratified analysis revealed that rs7186053 was associated with favorable event-free survival among patients with estrogen receptor (ER)-positive, progesterone receptor (PR)-positive or lymph node metastasis negative patients." (PMID 26285011, 2015). "Backward stepwise logistic regression analysis was performed for six factors (age, ER, PgR, HER2, lymph node metastasis, and SPARC) in 52 patients (two with no SPARC and histological assessments were excluded)." (PMID 28050738, 2017). "Furthermore, significant correlation was observed between MMP-2 expression and lymph node metastasis, but not other clinocopathological features, such as TNM stage, tumor size, distant metastasis, histological grade, estrogen receptor status and progesterone receptor status." (PMID 25816052, 2015).
ovarian carcinoma (64 papers, 1995 to 2025). A malignant neoplasm originating from the surface ovarian epithelium. "Previous studies showed that the progesterone receptor was associated with better rates of survival of ovarian cancer patients." (PMID 34771742, 2021). "The presence of progesterone receptor has been previously associated to better clinical outcome in patients with ovarian carcinoma." (PMID 30736825, 2019). "Hormone receptors are frequently expressed in ovarian carcinomas, and a recent meta-analysis of 35 studies reported that progesterone receptor (PR) expression is associated with longer survival." (PMID 28264438, 2017). "Subgroup analysis showed that progesterone receptor expression was associated with a favorable prognosis of unclassified ovarian cancer, European origin, and immunohistochemical detection method." (PMID 28415663, 2017). "The combined analysis of 26 studies showed that the expression of progesterone receptor was associated with a favorable OS of ovarian cancer (HR = 0.86, 95% CI = 0.78 to 0.95, P = 0.002)." (PMID 28415663, 2017). "Ovarian cancer is a major gynaecological cancer with different subtypes and studies have suggested that estrogen receptor (ER) or progesterone receptor (PR) positivity are associated with better clinical outcomes." (PMID 29137401, 2017). "The PgR +331 G/A promoter polymorphism has been extensively studied because of its relationship in different cancers such as breast, endometrial and ovarian cancer." (PMID 23349706, 2013). "To validate the association between the PgR +331G/A polymorphism and female reproductive cancer risk (breast, endometrial and ovarian cancer), we performed a meta-analysis of 19 studies (19,978 cases and 24,525 controls) by using the CMA Version 2 software." (PMID 23349706, 2013). "Lastly, while we evaluated the best PGR candidate variants suggested by the literature, it remains possible that other, as yet unidentified variants at the locus, influence ovarian cancer risk." (PMID 18219286, 2008). "Additionally, certain polymorphisms in the hormone-binding domain of the PGR gene have been associated with an increased risk of ovarian cancer." (PMID 37569592, 2023). "Progesterone receptor has been widely described to be associated with ovarian cancer." (PMID 28415663, 2017). "Previous studies have suggested that genetic variants in the progesterone receptor gene (PGR) may be associated with ovarian cancer risk, although results have been inconsistent." (PMID 18219286, 2008). "In summary, this meta-analysis shows that progesterone receptor positivity is associated with an improved OS and DFS/PFS/RFS, and progesterone receptor expression could be an indicator of a favorable prognosis in ovarian cancer patients, especially when measured by immunohistochemistry." (PMID 28415663, 2017). "Thus, loss of progesterone receptor maybe involved in the etiology and progression of ovarian cancer." (PMID 28415663, 2017). "It was reported that progesterone receptor positivity is proved to be an independent prognostic variable of improved progression for free-survival among patients with ovarian cancers." (PMID 39090421, 2025). "Progesterone rapidly induces ovarian cancer cell death through non‐genomic actions mediated by the membrane progesterone receptor (mPR)." (PMID 40270435, 2025). "Several clinical guidelines recommend endocrine therapy in relapsed ovarian cancer based on estrogen and progesterone receptor expression levels in primary HGSOC patients." (PMID 36430718, 2022). "The prognostic role of estrogen and progesterone receptor expression in ovarian cancer is well established." (PMID 36430718, 2022). "A notable example of this category of patients undergoing treatment currently is the one identified with BRCA mutations for breast and ovarian cancer, human epidermal growth factor receptor 2 (HER2), and progesterone receptor (PR) for breast cancer." (PMID 35775004, 2022).
ovarian carcinoma (continued). "Future studies should also consider the relationship between different expression profiles of estrogen and progesterone receptor positivity and negativity in ovarian cancer." (PMID 36430718, 2022). "Overall, our observations strongly support the early use of endocrine therapy in ovarian cancer patients owing to decreased and/or lost progesterone receptor expression during disease progression." (PMID 36430718, 2022). "KRT17 is a marker of cervical and ovarian cancer, and PGR plays a role in estrogen and progesterone signaling." (PMID 36389068, 2022). "In ovarian cancer, the progesterone receptor (PR‐B) induces cell senescence through FOXO1, and one of the characteristics of aging cells is the upregulation of FOXO1 expression." (PMID 34825509, 2021). "Not only are PGRMC1 and PGRMC2 expressed in ovarian cancer, but the nuclear progesterone receptor (PGR) is also expressed." (PMID 34885064, 2021). "Ovarian cancers have been shown to express hormone receptors, progesterone receptor (PR) and estrogen receptor (ER), which correlate with the survival in some ovarian tumor entities." (PMID 32612269, 2020). "Recently, FoxO1 has been shown to induce cellular senescence in ovarian cancer cells by the co-recruitment with progesterone receptor to the p21 promoter region." (PMID 32398756, 2020). "PgR activation induces apoptosis, cell cycle arrest and senescence in ovarian cancer cells, which strongly suggests the modulation of PgR levels and/or activity as a form of endocrine treatment of EOC." (PMID 30791364, 2019). "This study supports the importance of progesterone and the presence of progesterone receptor in the reduction of ovarian cancer progression in the endometrioid ovarian carcinoma." (PMID 30736825, 2019). "The effect is evident in endometrioid histological subtype and it is related to the presence of progesterone receptor in the ovarian carcinoma." (PMID 30736825, 2019). "On the other hand, the decreased PGR expression altered the insensitivity of various epithelial ovarian cancer cells to the anti-proliferative properties of P4." (PMID 29603059, 2018). "A marked downregulation of progesterone receptor mRNA expression was noted in ovarian cancer cell lines when compared with normal ovarian surface epithelium cells." (PMID 28415663, 2017). "Progesterone receptor expression can be used as a favorable prognostic predictor in ovarian cancer managements." (PMID 28415663, 2017). "Nevertheless, the expression of progesterone receptor was irrelevant with OS of ovarian cancer patients by using other detection methods (n = 3, HR = 0.70, 95% CI = 0.49 to 1.01, P = 0.055, I2 = 36.9%)." (PMID 28415663, 2017). "Many studies have investigated the relationship between progesterone receptor and ovarian cancer patient outcome." (PMID 28415663, 2017). "In order to address the disagreement of progesterone receptor in ovarian cancer survival, we conducted this meta-analysis." (PMID 28415663, 2017). "In this study, we performed a meta-analysis of published studies to assess the prognostic value of progesterone receptor in patients with ovarian cancer." (PMID 28415663, 2017). "Relevant articles on progesterone receptor and ovarian cancer prognosis were identified via a thorough search of PubMed, Embase and Cochrane Central." (PMID 28415663, 2017). "The estrogen receptor (ER) and progesterone receptor (PR) mediate the effects of sex hormones on proliferation and apoptosis of ovarian cancer cells." (PMID 29137401, 2017). "The interaction of progesterone and progesterone receptor (PR) in ovarian cancers has been focused on by a series of studies." (PMID 23554793, 2013). "Clinical outcome in ovarian carcinoma is predicted by progesterone receptor status, indicating an endocrine aspect to this disease." (PMID 7880723, 1995).